AXL (AXL receptor tyrosine kinase)
Diseases named in the same sentence as AXL in open-access papers (continued):
Sharing a sentence is not in itself a finding about the gene and the disease.
infection (continued). "Tyrosine-protein kinase receptor UFO (AXL) and neuropilin-1 (NRP1), a newly discovered viral receptor of SARS-CoV-2, promote the entry of SARS-CoV-2 into host cells and infection." (PMID 37644471, 2023). "Based on the analysis using protein sequences and models, we predicted that AXL and ACE2 receptors in chickens could be used as binding sites for emerging SARS-CoV-2 variants in the future; these sites help the virus break through the barrier and cause intracellular infection in chickens." (PMID 37644471, 2023). "Tyrosine-protein kinase receptor UFO (AXL), Neuropilin-1 (NRP1), and CD209 act as SARS-CoV-2 receptors which play critical roles in SARS-CoV-2 invasion and infection." (PMID 36008961, 2022). "The latest research suggests that AXL is a candidate receptor for SARS-CoV-2, which can promote the infection of lung and bronchial epithelial cells." (PMID 35450063, 2022). "The AXLneg clone, which expressed undetectable levels of AXL protein, supported dramatically lower SARS-CoV-2 virus loads at a range of input MOIs and the low level of infection that was poorly inhibited by bemcentinib." (PMID 34797899, 2021). "In total, our findings provide evidence that PS receptors facilitate infection of the pandemic coronavirus SARS-CoV-2 and suggest that inhibition of the PS receptor AXL has therapeutic potential against SARS-CoV-2." (PMID 34797899, 2021). "Consistent with an important role for AXL in SARS-CoV-2 infection, when these cells were treated with 1 μM bemcentinib at the time of infection, the fraction of viral transcripts dropped precipitously, decreasing to ~10% of the total reads." (PMID 34797899, 2021). "AXL and GAS6 expressions are upregulated in the gingival epithelium or blood vessels of mice after infection by P. gingivalis, whereas subsequent infections significantly reduce their expression levels." (PMID 34734092, 2021). "Because pre-treatment of fcMSCs with either anti-AXL antibody or warfarin only partially decreased cytotoxic effect of the virus, additional mechanisms involved in ZIKV entry/infection in these cells must also exist." (PMID 32941515, 2020). "Of note, while GAS6 and AXL are both augmented in the plasma of SARS-CoV-2 positive patients, GAS6 decreased in time in those patients that survived the infection." (PMID 32998369, 2020). "Upon infection, GAS6 as well as AXL were detected in LECs, suggesting that GAS6 increases permeability similar to blood endothelial cells." (PMID 29967614, 2018). "Furthermore, the ability of Csf1r-Cre+Axlfl/fl infected mice to mount protective adaptive antiviral responses is consistent with the preserved expression of AXL in lung DCs and the lack of increased susceptibility to infection in this conditional knock out line." (PMID 27350258, 2016). "Both AXL and SOCS3 were up-regulated approximately 2 fold in JFH1 infected cells (minimum 2 passages, 1 week post infection, 90% infectivity), but were surprisingly down-regulated in a stable cell line of Huh-7s harbouring a genotype 2a SGR." (PMID 26313459, 2015). "While both chimeric viruses replicated at lower levels than wild type JFH1, both induced significant AXL and SOCS3 up-regulation, albeit more potently following infection with the genotype 1b chimera." (PMID 26313459, 2015). "The mechanism by which ZIKV utilizes AXL for infection in the SNB-19 cells does not require innate immune suppression by AXL but likely relates to virion structural features that influence attachment during the subsequent rounds of infection." (PMID 40062839, 2025). "Importantly, CHV-I infection of AXL KO cells resulted in only a minimal reduction in viral protein as compared to WT cells, while CHV-II only showed infection in AXL KO cells at higher MOIs and more closely tracked with the infection phenotype of ZIKV." (PMID 40062839, 2025).
infection (continued). "The interaction study of NTD from BCoV/S with Bovine AXL, exhibited low binding affinity with NTD of BCoV/S with multiple non-covalent interactions, suggesting less possibility of its role in infection alone or with its synergistic effect with other receptors such as ACE2." (PMID 39941096, 2025). "However, an AXL inhibitor Bemcentinib (BGB324, R428) that was previously shown to inhibit Zika also lowered the infection of LUHMES at 1 μM." (PMID 40733616, 2025). "We speculate that the chalcone-mediated inhibition of viral entry is not likely because all four viruses tested here bind to different cellular receptors to initiate the infection: sialic acid for PIV5, DC-SIGN for LACV, AXL for ZIKV, and TMPRSS2 for OC43." (PMID 41008592, 2025). "R428 treatment inhibited SFTSV infection dose-dependently, and AXL-ΔCT expressing HEK293 cells (HEK293AXL-ΔCT) showed significantly lower infection rates compared to full-length AXL-expressing cells (HEK293AXL)." (PMID 40853130, 2025). "We also validate the functional role of AXL as a crucial receptor for ZIKV entry in DSCs and demonstrate that targeted inhibition of ligand-receptor interaction at the early stage of the infection is effective in drastically reducing virus pathogenesis at the maternal-fetal interface." (PMID 36483552, 2022). "siRNAs specific for NRP1, but not AXL, strongly inhibited the infection of astrocytes by SARS-CoV-2, as assessed by the reduced expression of viral nucleocapsid (N) mRNA." (PMID 36314791, 2022). "Later, other receptors and entry cofactors of SARS‐CoV‐2 were uncovered, including AXL, NRP1, SCARB1 etc.,27, 28, 29 which may explain its infection in tissues with low ACE2 expression." (PMID 35917402, 2022). "However, when low levels of ACE2 were co-expressed with either AXL or TIM-1, the combinations enhanced infection over that observed with ACE2 alone." (PMID 34797899, 2021). "In a study of ZIKV tropic cells (NPCs), depletion of AXL fails to protect human neural progenitor cells and cerebral organoids from the infection of ZIKV." (PMID 33954117, 2021). "Nevertheless, further investigation is needed to determine whether AXL and ACE2 utilize the same co-factors or are involved in similar infection processes." (PMID 33420426, 2021). "While AXL is not strictly required for ZIKV to initiate a productive infection in mice, its tissue distribution can sometimes be correlated with variable sensitivity to ZIKV." (PMID 34578404, 2021). "Many reports have shown that the AXL and TYRO3 of the TAM receptors could potentiate the infection of various viruses in different pathways." (PMID 32172658, 2020). "AXL and MER facilitate infection of a broad spectrum of viruses." (PMID 32695074, 2020). "We next examined whether AXL and GAS6 are expressed on lymphatic endothelial cells (LECs), and if the infection alters their expression pattern." (PMID 29967614, 2018). "However, in placenta cells, we saw that siRNA against TLR8 significantly decreased AXL expression after three days, with a similar downregulation also observed after TLR7 knockdown three days after infection." (PMID 30453684, 2018). "It was also shown that the non-enveloped virus SV40 can engage AXL directly by structural mimicry to facilitate infection." (PMID 27350258, 2016). "However, the precise relationship between bovine ACE2, AXL, NRP1, and the S protein in terms of predicting infection capability remains unclear." (PMID 38012648, 2023). "Taken together, AXL should not be a main receptor for SARS-CoV-2 in Jurkat cells but it may contribute to infection." (PMID 35277473, 2022). "Inhibition of AXL, a potential entry receptor of ZIKV identified in non CNS cells, did not mitigate ZIKV-induced pathogenic effects or pathogenesis infection in 24 day old cerebral organoids, indicating that AXL is not essential for infection." (PMID 35337041, 2022).
infection (continued). "Future studies involving knocking down AXL in A549 CD147 KD cells and co-expressing various alternative receptors in hACE2 null cells promise to provide a better understanding of whether these receptors act independently or in concert for infection." (PMID 34064066, 2021). "Considering our observation that JUNV modulates macrophage polarization and that AXL and MERTK are differentially expressed in pro-inflammatory M1 and anti-inflammatory M2 macrophages, respectively, we next evaluated TAM expression in HMDM after infection with both strains." (PMID 31695702, 2019). "Fortunately, the apparent contradiction in these findings could be tentatively explained by another study documenting that AXL is essential for infection of human glial cells (astrocytes and microglia), but not for human neural progenitor cells." (PMID 29937727, 2018). "However, the ocular abnormalities were shown to be independent of AXL or MER, given that AXL−/−, MER−/−, and AXL−/− MER−/− double knockout mice sustained levels of infection similar to those of control animals." (PMID 30319635, 2018). "However, AXL is not the only receptor used during infection in the brain." (PMID 40573410, 2025). "The antibody inhibited infection in DC-SIGN-expressing cells but not in AXL-expressing cells, indicating a unique SFTSV Gn-independent, AXL-mediated entry pathway." (PMID 40853130, 2025). "There are possibilities that other receptor candidates, such as CD147, AXL and NRP1, do not contribute to SARS-CoV-2 infection in iPSC-BMELCs, as their inhibitors had little inhibitory effect on the infection." (PMID 38584257, 2024). "The AXL-specific inhibitor bemcentinib inhibits SARS-CoV-2 infection in various lung cell lines, including some with low ACE2 but does not inhibit infection of Calu-3 cells, which express high levels of TMPRSS2." (PMID 36423144, 2022). "Soluble human AXL, but not ACE2, blocked SARS-CoV-2 virus pseudotype infection in H1299 cells, confirming that AXL is required for SARS-CoV-2 entry into pulmonary epithelial cells." (PMID 33420426, 2021). "Knocking out AXL, but not ACE2, significantly blocked SARS-CoV-2 virus pseudotype infection in H1299 cells." (PMID 33420426, 2021). "LCMV-WE infection also induced expression of a non-conventional virus receptor, AXL-1, from the TAM (TYRO3/AXL/MERTK) family of receptor tyrosine kinases and this expression correlated with proliferation." (PMID 25822203, 2015). "Notably, AXL is highly expressed in respiratory cells, unlike ACE2, suggesting its importance in infections by respiratory viruses such as SARS-CoV-2." (PMID 40649848, 2025). "Our data showed that AXL knockdown could not block SARS-CoV-2 infection, but an AXL overexpression could slightly enhance the infection (1.5-fold)." (PMID 35277473, 2022). "Since the binding, internalization and infection of SARS-CoV-2 was greatly reduced but not completely abolished in AXL-KO H1299 cells, additional receptor(s) other than AXL and ACE2 which mediates viral entry may exist." (PMID 33420426, 2021). "In contrast, PS receptors AXL and TIM-1 by themselves did not facilitate infection of SARS-CoV-2." (PMID 34797899, 2021). "Downregulating AXL, but not ACE2, significantly reduced infection of pulmonary cells by SARS-CoV-2." (PMID 33420426, 2021). "This increase in infectivity was associated with changes in blood brain barrier permeability, suggesting that AXL and MER do not serve exclusively as receptors and might have other roles in WNV infection of the brain." (PMID 30319635, 2018).
infection (continued). "While MER expression was not detectable, AXL was expressed by unstimulated T-HESC and, of note, it was upregulated in dT-HESC (RFI: 2.76 vs. 1.64, respectively), consistently with the higher infection efficiency observed in these experimental conditions." (PMID 28281680, 2017). "Interestingly, the transfection of AXL or Tim1 does not promote ACE2-mediated viral entry in cells co-transfected with TMPRSS2, and infection was insensitive to cysteine protease inhibitor E-64, indicating that PS receptors are not required for plasma membrane-mediated infection." (PMID 36423144, 2022). "Expression of members of the TIM (TIM-1 and TIM-4) and TAM (AXL) families of PS receptors enhance SARS-CoV-2 binding to cells, facilitate internalization of fluorescently-labeled virions and increase ACE2-dependent infection of SARS-CoV-2; however, PS receptors alone did not mediate infection." (PMID 34797899, 2021).
adenocarcinoma (8 papers, 2016 to 2023). A common cancer characterized by the presence of malignant glandular cells. "Altogether, our study showed that the CTC presence one month after surgery was an independent prognostic factor for RFS, and the CTC presence six months after surgery and the tissue AXL expression were independent prognostic factors for OS in adenocarcinoma patients." (PMID 31703465, 2019). "Interestingly, miR-155 expression was inversely correlated with IL6R and AXL, which were at the same time associated with the presence of EMT CTCs in adenocarcinoma." (PMID 31703465, 2019). "The multivariate regression analysis revealed that the presence of CTC3 (HR = 10.8, 95% CI = 1.54–76.4, p = 0.017) and high AXL expression (HR = 15.7, 95% CI = 1.63–150.7, p = 0.017) were the only independent prognostic factors for OS in adenocarcinoma patients." (PMID 31703465, 2019). "In the adenocarcinoma group, a moderate agreement between c-MYC and AXL was found using the Kappa coefficient of agreement, since it was seen 28 (71.8%) concordant cases (c-MYC+/AXL+ or c-MYC- /AXL-) and 11 (28.2%) discordant cases." (PMID 33759958, 2021). "Our study could provide the rationale for the inclusion of tissue AXL expression and CTC EMT activation as potential biomarkers of activity for these agents in early stage adenocarcinoma." (PMID 31703465, 2019). "Moreover, tissue AXL expression and CTC EMT activation could potentially represent biomarkers for the stratification of adenocarcinoma patients that might benefit from new adjuvant therapies." (PMID 31703465, 2019).
hematologic malignancies (6 papers, 2016 to 2025). "Currently consolidated in hematological malignancies and rapidly evolving even in solid tumors, anti-AXL therapies are continuously enriched with new inhibitors." (PMID 33182542, 2020). "MERTK and AXL are both members of the TAM family receptor tyrosine kinases and MERTK has been validated as a target in AML and other hematologic malignancies." (PMID 29806049, 2017). "Targeted inhibition of members of the TAM (TYRO-3, AXL, MERTK) family of receptor tyrosine kinases has recently been investigated as a novel strategy for treatment of hematologic malignancies." (PMID 27834816, 2016). "In summary, targeted inhibition of members of the TAM (TYRO-3, AXL, MERTK) family of receptor tyrosine kinases has recently been investigated as a novel strategy for treatment of hematologic malignancies." (PMID 27834816, 2016).
kidney diseases (4 papers, 2020 to 2025). "Drawing from other research, the Gas6/AXL pathway has been implicated in the pathogenesis of kidney diseases." (PMID 37813528, 2023). "We evaluated the effect of AXL inhibition on kidney diseases in NEP25 mice using CH5451098." (PMID 32324796, 2020). "Recently, Mer and Tyro3 have been reported to suppress kidney dysfunction, which means the blockade of AXL and induction of Mer and Tyro3 signaling might be a promising way to cure the kidney diseases in future." (PMID 32324796, 2020). "Therefore, in this study we used the potent and selective AXL inhibitor CH5451098 to elucidate the role of Gas6/AXL in kidney diseases." (PMID 32324796, 2020).
neurodegenerative disease (4 papers, 2021 to 2025). A disorder of the central nervous system characterized by gradual and progressive loss of neural tissue and neurologic function. "Overall, the emerging evidence suggests that dysregulation of MERTK and AXL is a feature broadly shared by neurodegenerative disease and neuroinflammation." (PMID 40596721, 2025). "It is worth noting that AXL expression is upregulated in many neurodegenerative disease models, proposing a connection between abnormal microglia phagocytosis and neurodegenerative disease development." (PMID 34751640, 2021).
breast (3 papers, 2020 to 2025). "In summary, our data demonstrate that AXL activation protects alcoholic fatty liver against ischemia-reperfusion injury by suppressing ER stress and mitochondria-associated apoptosis." (PMID 39897049, 2025). "EGCG reversed cisplatin resistance by downregulating AXL and TYRO3 expression in NSCLC and sensitizing 5-FU-resistant colorectal cancer." (PMID 32051483, 2020).
heart disease (3 papers, 2019 to 2023). "Soluble AXL has been used as a plasmatic prognostic biomarker in several heart diseases and settings." (PMID 31181097, 2019). "Studies using preclinical models have shown that the AXL receptor tyrosine kinase could be considered a potential target in cardiac diseases." (PMID 36983628, 2023).
cardiovascular disease (2 papers, 2024 to 2025). "Soluble AXL (sAXL) has garnered significant attention in the field of cardiovascular diseases (CVD) as a biomarker in recent years." (PMID 40933570, 2025). "Importantly, this study serves as a preliminary exploration of the implications of the Gas6/AXL complex, indicating the need for further relevant investigations beyond cardiovascular disorders." (PMID 40933570, 2025).
GI neoplasms (2 papers, 2023 to 2025). "High expression of AXL has been reported in a variety of primary GI tumors and metastases and linked to poor clinical prognosis." (PMID 37469409, 2023).
Hematological Cancers (2 papers, 2019 to 2020). "The ongoing clinical trials, development of even more specific inhibitors, and new combination strategies, will determine the future direction of AXL inhibitors in the treatment of hematological cancers." (PMID 31694201, 2019). "A summary of available AXL inhibitors, of which the majority are non-specific multi-kinase inhibitors, in a preclinical or clinical setting for hematological cancers will be provided as well." (PMID 31694201, 2019).
inflammation (2 papers, 2022 to 2023). Aberrant reaction of the microcirculation characterized by movement of fluid and leukocytes from the blood into extravascular tissues. "GAS6 is also known to be expressed in chronic inflammatory conditions, and GAS6 deficiency has been shown to prevent liver inflammation and fibrosis, potentially by restoring AXL on KCs." (PMID 37004869, 2023). "This suggested a role for GAS6/AXL signaling and the development of lung inflammation in this model of PE." (PMID 35741013, 2022). "Furthermore, the fact that the lung infiltration and pro-inflammatory cytokines are reduced during AXL inhibition confirms a possible direct role for Gas6/AXL signaling in lung inflammation and the development of PE." (PMID 35741013, 2022).
bacterial infection (1 paper, 2021). "AXL was also found to be activated and involved in bacterial infection-mediated inflammatory responses." (PMID 34439388, 2021).
psychiatric disorder (1 paper, 2021). A disorder characterized by behavioral and/or psychological abnormalities, often accompanied by physical symptoms. "Thus, based on AXL-induced phagocytic astrocytes that respond to active microglia-derived GAS6 after TBI, we connected the glial function with acute neurological and later psychiatric disorders that could be manipulated in the early stages." (PMID 34233703, 2021).
reproductive diseases (1 paper, 2023). "AXL is implicated in reproductive diseases including some forms of idiopathic hypogonadotropic hypogonadism and evidence suggests that AXL is required for normal spermatogenesis." (PMID 37396176, 2023).